RAB5A (RAB5A, member RAS oncogene family)
Diseases named in the same sentence as RAB5A in open-access papers (continued):
Sharing a sentence is not in itself a finding about the gene and the disease.
cancer (70 papers, 2010 to 2026). A tumor composed of atypical neoplastic, often pleomorphic cells that invade other tissues. "This study shows that unjamming, mediated by the RAB5A GTPase, alters carcinoma spheroid fluidity, rigidity, and rewires adhesion mechanics to drive supracellular active wetting as a new mode of tumor expansion." (PMID 40712149, 2025). "Intriguingly, the present study has systematically illustrated the cancer‐related behaviour of RAB5A, a member of the Rab GTPases subfamily, and its upstream relation with the m6A‐modulator ALKBH5." (PMID 37203239, 2023). "Previous researchers found that RAB5A can accelerate the progress of cancer by affecting the migration of cancer cells." (PMID 35059464, 2022). "Nevertheless, these results, in which knockout of RAB5A or CapZβ (two proteins involving in the endocytosis) inhibited cell migration and cancer metastasis, support the role of endosomal trafficking in V1-mediated migration and metastasis inhibition." (PMID 33564074, 2021). "Both migration and invasion data suggest that Rab5a activation by trypsin not only induces MVs generation from the cell surface but also promotes cancer cell metastasis by virtue of increasing cell migration and invasion." (PMID 29743547, 2018). "RIN1 interacts with RAB5A, which is connected to genes that are involved in cancer cell epithelial-to-mesenchymal transition." (PMID 26515236, 2015). "We observed that the depletion of Rab5a not only decreased cancer cell motility and invasiveness, but also inhibited the formation of filopodia and lamellipodia protrusions." (PMID 21849022, 2011). "Rab5a influences cancer cell motility and invasion by regulating the expression levels and activities of integrins and their downstream signaling molecules." (PMID 21849022, 2011). "Since Rab5a has been shown to influent cancer cell invasiveness and mobility, we focus on the effects of Rab5a depletion on the actin cytoskeleton organization." (PMID 21849022, 2011). "Since Rab5a has been identified to involve in cancer cell motility and invasiveness we set out to define the effects of Rab5a knockdown on integrin-mediated signaling molecules." (PMID 21849022, 2011). "RAB5A regulates intracellular vesicle transport resulting in cancer cell invasion and metastasis." (PMID 40381373, 2025). "RAB5A was best known as a master regulator of intracellular vesicle transport and could induce cancer cells invasion and metastasis." (PMID 37203239, 2023). "RAB5a overexpression has been identified to be involved in cancer cell motility and invasiveness." (PMID 35631574, 2022). "RAB5A is a constitutively expressed protein, and utilization as a biomarker will depend on the establishment of a threshold that separates RAB5Ahigh and RAB5Alow expressing cancer." (PMID 34741021, 2021). "This signifies that more pro-metastatic MVs count in cancer patients’ blood may result from PAR2 mediated Rab5a activation as observed intensely in our in vitro system." (PMID 29743547, 2018). "Rab5a immunostaining was observed to mainly localize in the cytoplasm and membrane of cancer cells." (PMID 21849022, 2011). "Recent findings have reported that Rab5a gene was involved in the progression of cancer." (PMID 21849022, 2011). "Silencing of Rab5a expression significantly decreased cancer cell motility and invasiveness." (PMID 21849022, 2011). "Only a few studies have shown that Rab5a was involved in the progression of cancer." (PMID 21849022, 2011). "Rab5A is overexpressed in several cancer types, including breast and ovarian cancers, hepatocellular carcinoma and oral squamous cell carcinoma, where it acts as an oncoprotein, stimulating cancer proliferation and invasion and thus promoting the malignant phenotype." (PMID 39839669, 2024).
cancer (continued). "Thus, HER2-expressing cancers with low RAB5A do better on trastuzumab as compared to T-DM1." (PMID 34741021, 2021). "However, the link between Rab5a and integrin-mediated signaling pathway and the exact roles of Rab5a in cancer progression remain unclear." (PMID 21849022, 2011). "Therefore, the overexpression of Rab5a in cancer may enhance the integrin-mediated signaling pathway, and induce the cancer cell migration and invasion." (PMID 21849022, 2011). "Three of the autophagy targets of miR-101 (RAB5A, ATG4D and STMN1) have been validated in human cancer models." (PMID 29089869, 2017). "The expression of RAB5A and EEA1 were significantly increased in aggressive cancer tissue compared to indolent diseased tissue (P ≤ 0.05)." (PMID 26473288, 2015). "However, the exact role of Rab5a in cancer cell invasion and metastasis is still unknown." (PMID 21849022, 2011). "Other exosomal proteins have also been identified as important predictive biomarkers of GIC owing to create cancer-friendly condition to promote cancer metastasis, like exosomal Formin-like 2 (FMNL2), cytotoxic T lymphocyte antigen 4 (CTLA-4), RAB5A, aspartate β-hydroxylase, and so on." (PMID 38561768, 2024). "Clathrin, caveolin, Rabs (Rab4, Rab5A, Rab1A, Rab2A) as well as their effectors (Rab25, Vav1, Rab coupling protein,cdc42, VSP39), can contribute to the processes of cancer cell survival and metastasis, and cancer stem cell emergence." (PMID 29409507, 2018). "Moreover, the correlation between increased RAB5A expression and decreased PIK3R1 expression in cancer warrants further investigation, as a possible feature of oncogenic adaptation where metastasis via Rab5-mediated cell migration progresses unchecked due to loss of regulation by p85α." (PMID 30650664, 2019). "Interestingly, depletion of Rab5a, 11b or 21 in carcinoma cells did not affect their ability to invade into matrix that had previously been remodelled by fibroblasts." (PMID 19953096, 2010). "The changes in APPL1 (3p21), RAB5A (3p24) and EEA1 (12q22) and RAB4A (1q42) in PIN or primary cancer tissue compared to their expression in non-malignant tissue may discriminate metastatic tissue and provide an avenue for monitoring disease progression." (PMID 26473288, 2015).
tumor (61 papers, 2009 to 2026). "In the current study, we revealed that RAB5A engages in the secretion of exosomes in TNBC cells, and exosomes derived from RAB5A-deficient cells cause the repolarization of tumor-associated macrophages by regulating miR-21." (PMID 38470169, 2024). "The knockdown of RAB5A leads to reduced tumor formation and impaired recruitment of tumor-associated macrophages in vivo." (PMID 39512697, 2024). "RAB4A promotes local invasion and distant metastasis of tumor cell lines, and RAB5A is associated with lymphatic and vascular invasion." (PMID 34350714, 2022). "Indeed, analysis of data from the 184 PC patients in the TCGA dataset revealed that enhanced RAB5A mRNA level was significantly associated with advanced tumor stage." (PMID 31387632, 2019). "Thus, we speculated that silencing RAB5A leads to an impairment of exosome biogenesis and delivery, subsequently causing a decrease in exosome secretion by tumor cells into the surroundings." (PMID 38470169, 2024). "In vivo experiments with xenograft models were performed, and RAB5A knockdown TNBC cells formed smaller and less aggressive tumors, with reduced recruitment of tumor-associated macrophages." (PMID 40691627, 2025). "The results showed that the expressions of YTHDC2, OAS1, and IFIT2 were all reduced in tumor tissues, whereas the expression of RAB5A was increased in tumor tissues." (PMID 39303913, 2024). "Apparently, when cultured with conditioned medium from macrophages incubated with RAB5A-depleted tumor exosomes, TNBC cell viability was suppressed, as were the migration and invasion capabilities." (PMID 38470169, 2024). "In vivo xenograft experiments further confirmed that RAB5A knockdown TNBC cells exhibited reduced tumor formation and impaired tumor-associated macrophage recruitment." (PMID 38470169, 2024). "By scanning miRNAs associated with macrophage polarization, we identified that miR-21 was the pivotal component in tumor cell-derived exosomes and played a key role in RAB5A-mediated macrophage polarization." (PMID 38470169, 2024). "In these tumours, RAB5A induction increased CytoDR, as expected, and was associated with an elevated number of γH2AX-positive cells, and increased levels of cGAS, which display a perinuclear dotted or crescent-like appearance." (PMID 36581770, 2023). "In human tumours, RAB5A displayed a graded increase in expression right at the margin of locally invasive foci." (PMID 36581770, 2023). "The number of tumor nodules per lung in mice implanted with RAB5A-knockout 4T1 cells was significantly lower than the mice implanted with control cells, which was similar to that in mice implanted with control cells treated with V1." (PMID 33564074, 2021). "Collectively, our study deepens the understanding of the role of RAB5A in tumor progression, proposes the potential molecular basis of RAB5A-mediated macrophage polarization in an exosomal miR-21-dependent manner, and helps to develop RAB5A- or exosome-based tumor therapeutic strategies." (PMID 38470169, 2024). "The depletion of Ras-related protein Rab-5A (RAB5A) in TNBC cells results in a significant reduction in exosome secretion and impairs the polarization of macrophages toward an M2 phenotype, which is associated with tumor progression." (PMID 39512697, 2024). "Furthermore, the levels of RAB5A mRNA were also increased in tumour tissues and showed a positive correlation with those of ALKBH5 in CRC tissues." (PMID 37203239, 2023). "Interestingly, this correlation analysis showed that mainly in the ICD clinical settings tumoural CALR levels positively correlated with the tumoural levels of phagocytosis-associated genes (especially PLA2G5, PLD1, RAB5A, VAMP7, STAB2)." (PMID 26314964, 2015). "Further studies on Rab5a may help us to fully understand tumor invasion and metastasis." (PMID 21849022, 2011).
tumor (continued). "Although we observed upregulation of all three Rab5 isoforms (Rab5A, Rab5B, Rab5C) in HCC, their individual contributions to lipid metabolism and tumor progression remain undefined." (PMID 40894643, 2025). "For example, biomarkers such as circulating tumor DNA (ctDNA) levels, SLC46A3 transporter status, and Ras-related protein Rab-5A (RAB5A) expression - an endocytic trafficking regulator from the RAS oncogene family - are under investigation." (PMID 41425250, 2025). "Macrophages stimulated with RAB5A-depleted TNBC cells (coculture, conditioned medium or exosomes) impaired their capability to promote the proliferation, migration, and invasion of tumor cells." (PMID 38470169, 2024). "Initial analyses revealed that mRNA expression of ITGB6, ERBB2, RAB5A, RAB7A, and GDI2 was all significantly higher in tumor tissue in comparison to normal tissue." (PMID 39630893, 2024). "In this study, we found that RAB5A knockdown significantly suppressed the proliferation, migration and invasion of CRC cells in vitro and inhibited subcutaneous tumour growth in vivo." (PMID 37203239, 2023). "This miRNA has been described as a tumor suppressor that inhibits the expression of oncogenes, such as RAB GTPase 5A (RAB5A) and enhancer of zeste 2 (EZH2)." (PMID 26895946, 2016). "The researchers found that RAB5A depletion in TNBC cells significantly reduced exosome secretion and blocked the ability to induce macrophage M2 polarization, a process known to promote tumor progression." (PMID 40691627, 2025). "Rab5a protein levels observed in tumor were higher than those observed in adjacent non-tumorous tissues (P < 0.05)." (PMID 21849022, 2011). "However, one of the limitations of this study was that no more experiments have been conducted to verify whether miR-301a-3p, RAB5A, and NFKBIA affect tumor progression." (PMID 36438897, 2022). "In addition, treatment of the mice implanted with RAB5A-knockout cells with V1 failed to further decrease the number of tumor nodules per lung." (PMID 33564074, 2021). "Intriguingly, tumor volume in mice injected with RAB5A-depleted MDA-MB-231 cells and THP-1 cells seem not to differ from those with only RAB5A-depleted MDA-MB-231 cell injection." (PMID 38470169, 2024).
RAB5A also shares sentences with these, for which no sentence is quoted: Down syndrome (8 papers); glioma (5); neuroblastoma (4); neurodegenerative disease (4); Salmonella Infections (4); amyotrophic lateral sclerosis (3); bacterial infection (3); cyst (3); dementia (3); infectious disease (3); liver cancer (3); metastatic cancer (3); triple-negative breast carcinoma (3); amyloid (2); amyotrophic lateral sclerosis 2 (2); bladder cancer (2); CMV infection (2); cognitive decline (2); colon carcinoma (2); diabetes (2); esophageal cancer (2); Huntington disease (2); leukaemia (2); Lewy body dementia (2); liver disease (2); lymph node metastasis (2); metastatic prostate carcinoma (2); neuropathy (2); non-small cell lung carcinoma (2); Obesity (2).
A further 57 diseases each share a sentence with RAB5A in 2 papers or fewer.